EDF1 (endothelial differentiation related factor 1)
Description:
Transcriptional coactivator stimulating NR5A1 and ligand-dependent NR1H3/LXRA and PPARG transcriptional activities. Enhances the DNA-binding activity of ATF1, ATF2, CREB1 and NR5A1. Regulates nitric oxid synthase activity probably by sequestering calmodulin in the cytoplasm. May function in endothelial cells differentiation, hormone-induced cardiomyocytes hypertrophy and lipid metabolism.
Synonyms: EDF-1; MBF1; CFAP280
Tractability: PROTAC: ubiquitination databases record sites on it; its protein half-life has been measured.
Gene: Protein-coding gene on chromosome 9 (136,862,115 to 136,866,312, reverse strand). Ensembl gene ENSG00000107223.
Subcellular location: Cytoplasm; Nucleus
Subcellular location (Human Protein Atlas): Cytosol; Nucleoli; Nucleoplasm
Gene Ontology:
Molecular function: protein binding; RNA binding; TFIID-class transcription factor complex binding; transcription coactivator activity; DNA binding
Biological process: positive regulation of DNA binding; endothelial cell differentiation; positive regulation of DNA-templated transcription; regulation of DNA-templated transcription; regulation of lipid metabolic process
Cellular component: cytoplasm; cytosol; nucleolus; nucleoplasm; nucleus
Genetic constraint (gnomAD): Loss-of-function variants: 5 observed, 21.17 expected, observed/expected ratio (o/e) 0.24, 90% interval 0.12 to 0.5. The upper end of that interval is the gene's LOEUF score, 0.5, which puts it in group 2 of 6, group 1 being the genes least tolerant of losing a copy. Missense variants: 137 observed, 200.45 expected, observed/expected ratio (o/e) 0.68, 90% interval 0.59 to 0.79. Synonymous variants: 96 observed, 80.4 expected, observed/expected ratio (o/e) 1.19, 90% interval 1.01 to 1.41.
Homologues: Orthologues: guinea pig EDF1 (99% identical), pig EDF1 (99% identical), mouse Edf1 (99% identical), dog EDF1 (92% identical), chimpanzee EDF1 (87% identical), tropical clawed frog edf1 (87% identical), zebrafish edf1 (82% identical), Drosophila melanogaster mbf1 (63% identical), Caenorhabditis elegans mbf-1 (55% identical).
Diseases named in the same sentence as EDF1 in open-access papers:
EDF1 is named in the same sentence as 11 diseases in open-access papers, as found by Europe PMC text mining. Sharing a sentence is not in itself a finding about the gene and the disease. The quoted sentences say what the papers report.
cardiomyopathy (1 paper, 2018). A disease of the heart muscle or myocardium proper. "Finally, decreased abundance of SMYD1, EDF1 and PDLI5 might provide molecular insights into the nature of the dilatative cardiomyopathy described in this mouse model." (PMID 30153853, 2018).
endothelial dysfunction (1 paper, 2021). In vascular diseases, endothelial dysfunction is a systemic pathological state of the endothelium (the inner lining of blood vessels) and can be broadly defined as an imbalance between vasodilating and vasoconstricting substances produced by (or acting on) the endothelium. "Since (i) Mg deficiency promotes endothelial dysfunction and (ii) EDF-1 plays a role in controlling endothelial performance, we investigated Mg-dependent modulation of EDF-1 in primary human EC." (PMID 33494333, 2021).
leiomyoma (1 paper, 2007). A well-circumscribed benign smooth muscle neoplasm characterized by the presence of spindle cells with cigar-shaped nuclei, interlacing fascicles, and a whorled pattern. "They included several genes such as NR2F1, PNN, Smad4, Smad5, STAT5B, JUN, TGIF2, and ATF1 that were over-expressed while RUNX3, STAT1, STAT6, EGR3, GAS7, Smad1, and EDF1 were underexpressed in leiomyomas as compared to keloid/incisional scars." (PMID 17718906, 2007).
infection (3 papers, 2015 to 2021). The state of being infected such as from the introduction of a foreign agent such as serum, vaccine, antigenic substance or organism. "Only 3 genes each in the spleen (B2m, Lst1 and Edf1) and the brain (Six6, Cd163 and Bmp10) were modulated at all three time points after V3034 infection." (PMID 28446152, 2017).
tumor (2 papers, 2011 to 2025). "Additionally, the tumor-inhibiting effect by knocking down EDF1 was rarely caused potential toxic effects, such as body weight loss, comparing with CDDP treatment." (PMID 39905449, 2025). "However, EDF1 overexpression enlarged tumor size compared to Ctrl, while down-regulation of EDF1 inhibited tumor growth and metastasis (spleen and liver), as validated by EDF1 and Ki67 staining." (PMID 39905449, 2025). "Furthermore, although EDF1 knocked down NB cells seemed more sensitive to cisplatin (CDDP), the reduction in tumor size." (PMID 39905449, 2025).
cardiovascular diseases (1 paper, 2018). "On these bases, we propose that EDF1 makes an important contribution to maintain endothelial integrity, and this may be crucial in the prevention of cardiovascular diseases." (PMID 29933613, 2018).
EDF1 also shares sentences with these, for which no sentence is quoted: bacterial infection (1 paper); cyst (1); magnesium deficiency (1); neuroblastoma (1); osteosarcoma (1).